SCRN3 (secernin 3)
Description:
Plays a role in thermal nociception.
Synonyms: FLJ23142; SES3
Tractability: PROTAC: ubiquitination databases record sites on it; its protein half-life has been measured.
Gene: Protein-coding gene on chromosome 2 (174,395,729 to 174,430,077, forward strand). Ensembl gene ENSG00000144306.
Subcellular location (Human Protein Atlas): Cytosol; Vesicles
Gene Ontology:
Molecular function: cysteine-type exopeptidase activity; dipeptidase activity
Biological process: detection of temperature stimulus involved in sensory perception of pain; proteolysis
Genetic constraint (gnomAD): Loss-of-function variants: 24 observed, 28.22 expected, observed/expected ratio (o/e) 0.85, 90% interval 0.62 to 1.2. The upper end of that interval is the gene's LOEUF score, 1.2, which puts it in group 5 of 6, group 1 being the genes least tolerant of losing a copy. Missense variants: 347 observed, 360.15 expected, observed/expected ratio (o/e) 0.96, 90% interval 0.88 to 1.05. Synonymous variants: 106 observed, 117.02 expected, observed/expected ratio (o/e) 0.91, 90% interval 0.77 to 1.07.
Homologues: Orthologues: chimpanzee SCRN3 (99% identical), macaque SCRN3 (97% identical), dog SCRN3 (91% identical), rabbit SCRN3 (89% identical), guinea pig SCRN3 (87% identical), pig SCRN3 (82% identical), mouse Scrn3 (81% identical), rat Scrn3 (80% identical), zebrafish scrn3 (62% identical), tropical clawed frog scrn3 (48% identical), Drosophila melanogaster CG10098 (25% identical). Paralogues in human: SCRN2 (53% identical), SCRN1 (51% identical).
Diseases named in the same sentence as SCRN3 in open-access papers:
SCRN3 is named in the same sentence as 3 diseases in open-access papers, as found by Europe PMC text mining. Sharing a sentence is not in itself a finding about the gene and the disease. The quoted sentences say what the papers report.
cardiovascular diseases (1 paper, 2021). "Specifically, let-7b-5p showed a higher abundance level in EA compared to HVs and has a binding site to Secernin 3 (SCRN3) mRNA target, which has not yet been reported to be related to any biological function in cardiovascular diseases." (PMID 33946378, 2021).
SCRN3 also shares sentences with these, for which no sentence is quoted: Alzheimer disease (1 paper); cancer (1).